EGFR (epidermal growth factor receptor)
Diseases named in the same sentence as EGFR in open-access papers (continued):
Sharing a sentence is not in itself a finding about the gene and the disease.
lung adenocarcinoma (continued). "To address these questions, we conducted a comprehensive study in a large cohort of Chinese patients with lung adenocarcinoma and determined the associations between 5 common driver genes (EGFR, KRAS, ALK, RET, BRAF) and pathological subtypes, as well as their combined impact on prognosis." (PMID 29137260, 2017). "Similarly, in cases of lung adenocarcinoma, the T790M mutation in EGFR, which was barely detectable in primary tumors, often became predominant after EGFR blockade." (PMID 28977029, 2017). "Even it has been proved that EGFR-TKIs had a better response in EGFR mutation selected lung adenocarcinoma, whether the EGFR-mutated LSCC patients can benefit more from the EGFR-TKIs remains unclear." (PMID 28881841, 2017). "Such oncogenic somatic alterations though vary across populations/ethnic groups, e.g. EGFR mutations are present in over 30% of East Asian lung adenocarcinoma patients, however, they are only found in ∼23%–25% of Indian and 10% of Western lung adenocarcinoma patients." (PMID 27998968, 2017). "In the Phase III LUX-Lung 3/6 (LL3/LL6) trials in epidermal growth factor receptor (EGFR) mutation-positive lung adenocarcinoma patients, we evaluated feasibility of EGFR mutation detection using circulating cell-free DNA (cfDNA) and prognostic and predictive utility of cfDNA positivity (cfDNA+)." (PMID 28006816, 2017). "Panobiostat sensitized lung adenocarcinoma cells including cells with K-ras (Kirsten rat sarcoma viral oncogene homolog) or epidermal growth factor receptor (EGFR) mutation to the anti-proliferative effects of the tyrosine kinase inhibitor erlotinib in the in vitro experiment." (PMID 28671573, 2017). "To choose miRNAs which shows statistically significant different expression according to EGFR mutational status in smoker males with early stage of lung adenocarcinoma, we attempted to obtain comparative miRNA profiles using paired plasma and tumor tissues from same patients." (PMID 29383112, 2017). "Ever-smokers with grade III lung adenocarcinoma had 1.8% incidence of EGFR mutations." (PMID 29232915, 2017). "Furthermore, cerebrospinal fluid is also under investigation as a source of ctDNA for mutation analysis; notably, EGFR mutations have been detected in ctDNA sampled from the cerebrospinal fluid of patients with lung adenocarcinoma and brain metastases." (PMID 27980215, 2017). "Furthermore, systematic genetic and histological analyses have been performed on tumor biopsies from 37 patients with drug-resistant lung adenocarcinoma carrying EGFR mutations." (PMID 27757846, 2017). "Targeted treatments with tyrosine kinase inhibitors (TKI) have become the first line therapy for patients with advanced lung adenocarcinoma bearing EGFR mutations or ALK rearrangement, thanks to the improved clinical response and tolerability profile of these drugs compared to standard chemotherapy." (PMID 28560038, 2017). "In Asians, ~50% of lung adenocarcinomas harbor EGFR mutations." (PMID 28076323, 2017). "The number of treatment options for lung adenocarcinoma (ADC) has increased in recent decades following the identification of sensitizing epidermal growth factor receptor (EGFR) mutations and anaplastic lymphoma kinase (ALK) rearrangements as molecular targets for effective agents." (PMID 28881674, 2017). "Considering the essential role of autophagy in EGFR-TKIs treatments, we hypothesized that genetic variants in autophagy core genes might contribute to outcomes of advanced lung adenocarcinoma treated with gefitinib." (PMID 29259263, 2017). "During the study period, 48 patients with stage IV lung adenocarcinoma harboring susceptible EGFR mutations who received afatinib as the first-line therapy were enrolled, of whom 29 (60.5%) and 19 (39.5%) received 30 mg and 40 mg daily as their initial treatment, respectively." (PMID 29237484, 2017). "Most of them focusing on the association of EGFR and lung adenocarcinoma or pan-NSCLC." (PMID 28387300, 2017).
lung adenocarcinoma (continued). "In Taiwan, the National Health Insurance Bureau has permitted the use of both 30 mg and 40 mg daily of afatinib as the first-line therapy for patients with advanced lung adenocarcinoma with activating EGFR mutations since May 2014." (PMID 29237484, 2017). "We likewise expected the pathways selected by MGSA for the mutation data would more effectively capture pathways known to be impacted by mutations that differ between lung adenocarcinoma and lung squamous cell carcinoma (e.g. pathways related to EGFR and Interleukin signaling (42 44))." (PMID 28472344, 2017). "In addition, we did not investigate the mutations of KRAS and ALK genes in EGFR-wt patients, which play a major role in the progression of lung adenocarcinoma and are mutually exclusive from EGFR gene mutations." (PMID 29383112, 2017). "In this study, bronchial nvasion was accurately assessed by preoperative bronchoscopy, combined with postoperative pathologies of pleural and lymph node metastases as well as EGFR gene mutation assays, to further elucidate local invasion in early resectable lung adenocarcinoma." (PMID 28253871, 2017). "Therefore, further multi-factor, large sample, and multi-center studies are needed to confirm the association of local structure invasion in early lung adenocarcinoma with EGFR." (PMID 28253871, 2017). "In lung adenocarcinoma, mutations and over expression in the EGFR gene leads to activation of the EGFR-MAPK pathway, which may influence cell proliferation, migration and survival." (PMID 29029422, 2017). "Furthermore, recurrent lung adenocarcinoma patients with high serological CEA levels have a higher EGFR mutation rate after surgery and higher serological CEA levels." (PMID 28705152, 2017). "In a subsequent phase IIB trial (LUX-Lung 7) afatinib conferred a significant benefit in prolonging PFS and time to treatment failure, but not overall survival (OS), compared to first-line treatment with gefitinib in patients with advanced EGFR mutation-positive lung adenocarcinoma." (PMID 29163842, 2017). "The tyrosine kinase inhibitors erlotinib and gefitinib show significant clinical responses in lung adenocarcinoma patients harbouring EGFR activating mutations, whereas dacomitinib, a pan-HER tyrosine kinase inhibitor has been shown to be beneficial in HER2-mutated lung tumours." (PMID 28750640, 2017). "Aberrant expressionof Rb is frequently occurred in lung adenocarcinoma patients with EGFR mutations and may be an important pathogenesis in patients with lung adenocarcinoma." (PMID 28532538, 2017). "Furthermore, we also investigated the specific molecular background of glucose metabolism in EGFR- or KRAS-mutated lung adenocarcinoma." (PMID 28422979, 2017). "Retrospectively included 282 patients who was pathologically proved as lung adenocarcinoma with known EGFR mutation status (mutations: 138 patients, female: 86, median age: 66 years; wildtype: 144 patients, female: 67, median age: 62 years) and their pre-treatment CT scans were analyzed." (PMID 28949965, 2017). "However, no previous study has compared the treatment efficacy of a different initial dose (30 mg or 40 mg daily) of afatinib as the first-line therapy in patients with lung adenocarcinoma harboring susceptible EGFR mutations." (PMID 29237484, 2017). "Therefore, in the present study, we investigated the impact of CEA, CYFRA 21-1, NSE and CA199 on the prognosis and prediction of TKI-treated stage IIIB and IV lung adenocarcinoma patients with EGFR-sensitive mutations." (PMID 29050327, 2017). "The LUX-Lung 7 trial reported that afatinib used as first-line treatment for patients with advanced lung adenocarcinoma and activating EGFR mutations significantly prolonged PFS and the time to treatment failure but not overall survival compared to gefitinib treatment." (PMID 29237484, 2017).
lung adenocarcinoma (continued). "During the study period, a total of 209 patients with stage IV lung adenocarcinoma harboring susceptible EGFR mutation who had received gefitinib as the first-line therapy were enrolled, and 86 of them had received cytotoxic chemotherapy as their second-line treatment." (PMID 28486985, 2017). "Our research highlights that combination of afatinib and autophagy inhibitor may be a promising approach to increase the sensitivity of lung adenocarcinoma cells harboring activating EGFR mutations to afatinib treatment." (PMID 28676644, 2017). "Clinical reports about all other single point-mutations, in-frame deletions, in-frame duplications or insertions are anecdotal, as are those about patients with NSCLC harbouring complex EGFRm, representing the 6% of all EGFR mutated lung adenocarcinoma in a described Asian population." (PMID 28427238, 2017). "In recent years, there have been dramatic advances in the treatment of lung adenocarcinoma because of the development of therapies targeting driver oncogene alterations, for example, drugs targeting the epidermal growth factor receptor (EGFR) mutation or the anaplastic lymphoma kinase (ALK) fusion." (PMID 28145884, 2017). "However, there are still limited studies regarding to circulating miRNA expression signatures which enable to distinguish mutation status of EGFR gene in lung adenocarcinoma male patients with smoking history." (PMID 29383112, 2017). "For the small subset of patients diagnosed with advanced lung adenocarcinoma carrying epidermal growth factor receptor (EGFR) mutations or anaplastic lymphoma kinase (ALK) rearrangements, several options including the tyrosine kinase inhibitors, erlotinib and gefitinib, are now available." (PMID 29262603, 2017). "Therefore, clarifying the clinical characteristics of early lung adenocarcinoma patients with EGFR mutation aims to provide a basis for clinical treatment." (PMID 28253871, 2017). "The use of HRT may modify the association of protective EGFR single nucleotide polymorphisms (SNPs) with lung adenocarcinoma risk." (PMID 28783064, 2017). "Our results confirmed the genomic instability between primary lung adenocarcinoma and brain metastasis, and a higher co-existence of EGFR and K-ras mutations than that of previously reported, which may be one of the causes of intrinsic resistance." (PMID 27070580, 2016). "Therefore, further analyses were focused on the association between the polymorphism of IFG1R gene and EGFR hotspot mutations in female lung adenocarcinoma patients." (PMID 27213344, 2016). "EGFR-mutated lung adenocarcinomas routinely develop resistance to tyrosine kinase inhibitors (TKI)." (PMID 27304188, 2016). "This study showed that the PIK3CA mutation could be detected in a small proportion (1.8%) of lung adenocarcinomas, but with high concomitant EGFR mutations." (PMID 27734950, 2016). "Because both EGFR and K-ras mutations are thought to be early events in lung adenocarcinoma and K-ras mutations are closely related to smoking status, the reported coexistence of EGFR and K-ras mutations only accounts for about 5% of patients with EGFR mutations." (PMID 27070580, 2016). "Our results also add another mechanism that low content of mutant EGFR DNA may cause the primary resistance of EGFR-TKIs in lung adenocarcinoma patients with common EGFR mutations." (PMID 27368002, 2016). "To date, only one other study has investigated the predictive value of metabolic and volumetric variables concerning the use of pretreatment 18F-FDG PET/CT in advanced lung adenocarcinoma patients stratified by EGFR mutation status using the RECIST 1.1 criteria." (PMID 27336755, 2016). "EGFR exon 19 deletion (del19) and exon 21 Leu858Arg substitution (L858R) make up around 90% of all EGFR mutation-positive lung adenocarcinomas, and are strongly associated with robust responses and improved progression-free survival (PFS) to EGFR tyrosine kinase inhibitors (EGFR-TKIs)." (PMID 27072585, 2016).
lung adenocarcinoma (continued). "Furthermore, another recent study found that EGFR mutation status was an independent prognostic factor for post-recurrence survival in patients with recurrent lung adenocarcinomas following curative resection." (PMID 27861565, 2016). "The frequency of EGFR mutations vary according to the population; in Caucasians EGFR mutations occurs in 10 to 15%, whereas in East Asia and Latin America these are more frequent occurring in 30 to 50% of lung adenocarcinoma patients." (PMID 27926478, 2016). "However, the risk factors for developing BM during the course of EGFR-TKIs therapy from EGFR-mutated advanced lung adenocarcinoma were rarely evaluated." (PMID 27626317, 2016). "In a lung adenocarcinoma simultaneously harboring multiple heterogeneous clones of EGFR mutation and K-ras mutation, the effect of EGFR TKIs may be limited only to the parts carrying EGFR mutation but not to the other parts carrying K-ras mutations." (PMID 27070580, 2016). "EGFR mutations were detected in 49.2% (494 of 1004) of lung adenocarcinomas." (PMID 27861565, 2016). "Many different mechanisms of drug resistance in EGFR-mutated lung adenocarcinoma cells have been proposed which could be investigated further in this model." (PMID 27501455, 2016). "Our results showed that IGF1R genetic variants are related to EGFR mutation in female lung adenocarcinoma patients and may be a predictive factor for tumor lymph node metastasis in Taiwanese patients with NSCLC." (PMID 27213344, 2016). "EGFR mutations are thought to occur mainly in lung adenocarcinoma." (PMID 26923333, 2016). "The epidermal growth factor receptor (EGFR) gene mutations are found in ~10% of lung adenocarcinomas in Caucasian population, but in 30% ~ 50% of Asian population, which define a substantial population that can benefit from the use of EGFR tyrosine kinase inhibitors (TKIs)." (PMID 27528220, 2016). "Because previous studies were conducted in limited populations such as patients with surgically resected or advanced lung adenocarcinomas, it has been difficult to reach comprehensive conclusions regarding the association between EGFR mutations and stage at diagnosis." (PMID 27861565, 2016). "EGFR mutations were detected in 49.2% of 1004 patients with lung adenocarcinomas." (PMID 27861565, 2016). "Four loci, 5p15.33 (TERT), 6p21.3 (BTNL2), 3q28 (TP63) and 17q24.2 (BPTF), previously shown to be strongly associated with overall lung adenocarcinoma risk in East Asians, were re-discovered as loci associated with a higher susceptibility to EGFR mutation-positive lung adenocarcinoma." (PMID 27501781, 2016). "In addition, we analyzed the association between the EGFR mutation status and histological subtypes in the subgroup of lung adenocarcinoma according to the 2011IASLC/ATS/ERS classification." (PMID 27527915, 2016). "In our study, 77 lung adenocarcinoma patients with common EGFR mutations were enrolled." (PMID 27368002, 2016). "A total of 1316 formalin-fixed, paraffin-embedded samples from surgical patients at Shanghai Pulmonary Hospital were initially screened, including 1107 cases of lung adenocarcinoma, of which 456 wild-type EGFR lung adenocarcinoma cases were analyzed for HER-2 mutation." (PMID 27793199, 2016). "In addition, tumor morphologic evolutions such as epithelial to mesenchymal transition and transformation to small cell lung cancer (SCLC), although uncommonly seen, have been associated with resistance to EGFR-TKI therapy in lung adenocarcinomas." (PMID 27488410, 2016). "To understand the impact of PIK3CA mutations on clinical characteristics and treatment response to epidermal growth factor tyrosine kinase inhibitors (EGFR TKIs) of lung adenocarcinoma, we examined PIK3CA and EGFR mutations in lung adenocarcinoma patients, and analyzed their clinical outcomes." (PMID 27734950, 2016). "Accordingly, combined EGFR and K-ras mutation analyses may be helpful in selection of treatment strategies for patients with lung adenocarcinomas." (PMID 27070580, 2016).
lung adenocarcinoma (continued). "In the present study, we reviewed 134 patients with EGFR-mutated advanced lung adenocarcinoma, investigated the possible risk factors for developing BM during the course of EGFR-TKIs therapy and tried to identify the potential patients most likely to benefit from PCI." (PMID 27626317, 2016). "In addition, two additional loci, HLA class II at 6p21.32 (rs2179920; P =5.1 × 10−17, per-allele OR=1.36) and 6p21.1 (FOXP4) (rs2495239; P=3.9 × 10−9, per-allele OR=1.19) were newly identified as loci associated with EGFR mutation-positive lung adenocarcinoma." (PMID 27501781, 2016). "Mutations on epidermal growth factor receptor (EGFR) of adenocarcinomas of lung have been found to be associated with increased sensitivity to EGFR tyrosine kinase inhibitors and K-ras mutations may correlate with primary resistance." (PMID 27070580, 2016). "Gefitinib is a specific and effective epidermal growth factor receptor tyrosine kinase inhibitors (EGFR-TKIs), and it has been studied and used to treat lung adenocarcinoma patients with activating EGFR mutations, such as exon 19 deletion and exon 21 L858R mutation." (PMID 27494877, 2016). "EGFR mutation was closely correlated to the histologic subtype of lung adenocarcinoma." (PMID 25715252, 2015). "However, in subgroup of lung adenocarcinoma, there was a borderline difference between PD-L1 expression level and EGFR mutational status (32/56 (57.1%) for wild type and 64/89 (71.9%) for mutant type, respectively, p=0.067)." (PMID 25895031, 2015). "Recently, it was shown that high PD-L1 expression was associated with the presence of epidermal growth factor receptor (EGFR) mutation in advanced lung adenocarcinoma and PD-L1 overexpression was considered as a poor prognostic indicator in EGFR wild-type patients but not in EGFR mutant patients." (PMID 26305724, 2015). "Therefore, a better understanding of the molecular mechanisms underlying lung adenocarcinoma cell proliferation and apoptosis, as well as their relationship with EGFR-TKIs, is needed for improving the treatment of lung adenocarcinoma more efficiently." (PMID 25925741, 2015). "A total of 1,201 patients with lung adenocarcinomas were screened for EGFR mutation status." (PMID 26354324, 2015). "Other studies showed that the restoration of miR-145 and miR-7 inhibited cancer cell growth in lung adenocarcinoma patients with EGFR activating mutation and could effectively target EGFR addicted and EGFR-TKI resistant tumors." (PMID 26273639, 2015). "EGFR TKIs might improve the survival outcomes of EGFR-mutated lung adenocarcinoma patients who experienced disease recurrence." (PMID 26486077, 2015). "A total of 1356 lung adenocarcinoma cases from April 2007 to May 2013 were sequenced for EGFR kinase domain mutations, KRAS mutations, HER2 kinase domain mutations, BRAF mutations, ALK fusions, ROS1 fusions, RET fusions and AKT1 mutations." (PMID 26486077, 2015). "To elucidate how EGFR signaling is linked to metabolic activity, we investigated the involvement of the RAS/MEK/ERK and PI3K/AKT/mammalian target of rapamycin (mTOR) pathways on metabolic alteration in lung adenocarcinoma (LAD) cell lines with activating EGFR mutations." (PMID 26023239, 2015). "Lung adenocarcinoma patients with EGFR gene mutations have shown a dramatic response to gefitinib." (PMID 25886066, 2015). "However, in the modern era of targeted therapy, clinicians have the option of treating lung adenocarcinoma patients harboring EGFR mutations with EGFR tyrosine kinase inhibitors (TKIs), which have improved the survival of such patients." (PMID 26338423, 2015). "Finally, we demonstrated that clinical samples of lung adenocarcinomas harboring the EGFR-L858R mutation exhibited increased surface expression of CXCR4." (PMID 26338423, 2015).